RNU6-316P (RNA, U6 small nuclear 316, pseudogene)
Gene: Small nuclear RNA gene on chromosome 18 (14,190,700 to 14,190,806, forward strand). Ensembl gene ENSG00000212329.
Homologues: Orthologues: macaque U6 (95% identical), dog U6 (72% identical), mouse Gm22279 (60% identical), mouse Gm54642 (60% identical), rat LOC120101210 (59% identical). Paralogues in human: RNU6-55P (98% identical), RNU6-954P (97% identical), RNU6-1193P (95% identical), RNU6-1269P (95% identical), RNU6-368P (95% identical), RNU6-538P (95% identical), RNU6-1320P (94% identical), RNU6-599P (94% identical), U6 (94% identical), U6 (93% identical), RNU6-821P (90% identical), RNU6-798P (88% identical), and 1286 more.